FAM81A (family with sequence similarity 81 member A)
Description:
Facilitates the interaction and assembly of proteins within the postsynaptic density by promoting the condensation of postsynaptic proteins via liquid-liquid phase separation. Required for neuronal activity. Accumulation at the postsynaptic density results in enlargement of dendritic spines.
Synonyms: MGC26690
Tractability: PROTAC: ubiquitination databases record sites on it.
Gene: Protein-coding gene on chromosome 15 (59,372,692 to 59,523,555, forward strand). Ensembl gene ENSG00000157470.
Subcellular location: Postsynaptic density; Cytoplasm
Subcellular location (Human Protein Atlas): Nucleoplasm; Cytosol
Gene Ontology:
Molecular function: protein binding; molecular condensate scaffold activity
Cellular component: cytoplasm; postsynaptic density; glutamatergic synapse; postsynaptic density, intracellular component
Genetic constraint (gnomAD): Loss-of-function variants: 18 observed, 42.68 expected, observed/expected ratio (o/e) 0.42, 90% interval 0.29 to 0.62. The upper end of that interval is the gene's LOEUF score, 0.62, which puts it in group 2 of 6, group 1 being the genes least tolerant of losing a copy. Missense variants: 368 observed, 454.26 expected, observed/expected ratio (o/e) 0.81, 90% interval 0.74 to 0.88. Synonymous variants: 179 observed, 154.53 expected, observed/expected ratio (o/e) 1.16, 90% interval 1.02 to 1.31.
Homologues: Orthologues: chimpanzee FAM81A (100% identical), macaque FAM81A (99% identical), pig FAM81A (94% identical), rat Fam81a (93% identical), rabbit FAM81A (93% identical), dog FAM81A (92% identical), mouse Fam81a (92% identical), guinea pig FAM81A (88% identical). Paralogues in human: FAM81B (33% identical).
Diseases named in the same sentence as FAM81A in open-access papers:
FAM81A is named in the same sentence as 6 diseases in open-access papers, as found by Europe PMC text mining. Sharing a sentence is not in itself a finding about the gene and the disease. The quoted sentences say what the papers report.
Arthritis (1 paper, 2025). Inflammation of a joint. "Interestingly, in response to DMM injury, LG/J mice develop robust synovial and meniscal calcification, correlated with SNPs relating to angiogenesis, bone metabolism/calcification, arthritis, and ankylosing‐spondylitis and gene transcripts of Aff3, Fam81a, Syn3, and Ank." (PMID 39930949, 2025).
depression (1 paper, 2024). "In addition, FAM81A is reported as one of the hub genes related to susceptibility to depression, suggesting that the expression level of FAM81A, which may affect neuronal activity, is involved in neuropsychiatric disorders, including major depression." (PMID 38452102, 2024).
cancer (3 papers, 2022 to 2025). A tumor composed of atypical neoplastic, often pleomorphic cells that invade other tissues. "As expected, these CNVs caused differential gene expression at these loci, such as LOXL1 and FAM81A implicated in cancer progression." (PMID 35986270, 2022). "There were significant differences in FAM81A, PCNT, and TMX4 expressions between tumor tissues and normal tissues in multiple types of cancer based on TCGA and GTEx." (PMID 40155922, 2025). "The paired sample analysis using TCGA database-sourced data showed the same noteworthy increase in the expressions of FAM81A and PCNT in cancers compared to paracancerous tissues." (PMID 40155922, 2025).
tumor (3 papers, 2022 to 2025). "Multivariate linear regression analysis identified SNPs in 11 genes (Sepsecs, Rhobtb1, Tsen15, Abcc3, Arid5b, Tnr, Dock2, Tti1, Fam81a, Stx6, and Oxr1) that were independently associated with the tumour multiplicities." (PMID 39067134, 2024). "We pooled all 20 genes (Stx6, Ramp1, Traf3ip1, Nckap5, Pfkfb2, Trmt1l, Rprd1b, Rer1, Sepsecs, Rhobtb1, Tsen15, Abcc3, Arid5b, Tnr, Dock2, Tti1, Fam81a, Oxr1, Plxna2 and Tbc1d31) together as the mouse tumour susceptibility gene signature (mTSGS)." (PMID 39067134, 2024). "SQWCF suppressed the mRNA and protein levels of FAM81A in tumor tissues, consistent with omics data." (PMID 40155922, 2025). "FAM81A is recently reported to have a potential role in the occurrence and development of tumor." (PMID 40155922, 2025). "Multivariate analyses flagged SNPs in 20 genes (Stx6, Ramp1, Traf3ip1, Nckap5, Pfkfb2, Trmt1l, Rprd1b, Rer1, Sepsecs, Rhobtb1, Tsen15, Abcc3, Arid5b, Tnr, Dock2, Tti1, Fam81a, Oxr1, Plxna2, and Tbc1d31) independently tied to various tumour characteristics, designated as a mTSGS." (PMID 39067134, 2024).
FAM81A also shares sentences with these, for which no sentence is quoted: major depression (1 paper); pancreatic cancer (1).